Y_RNA (Y RNA )
Gene: Miscellaneous RNA gene on chromosome 16 (30,471,587 to 30,471,703, forward strand). Ensembl gene ENSG00000222701.
Homologues: Orthologues: chimpanzee Y_RNA (99% identical). Paralogues in human: Y_RNA (70% identical), RNY3 (69% identical), Y_RNA (68% identical), RNY3P1 (68% identical), RNY3P9 (67% identical), Y_RNA (67% identical), RNY3P14 (66% identical), Y_RNA (66% identical), RNY3P16 (65% identical), RNY3P4 (65% identical), Y_RNA (65% identical), RNY3P2 (64% identical), and 83 more.